PTPRH (protein tyrosine phosphatase receptor type H)
Diseases named in the same sentence as PTPRH in open-access papers:
PTPRH is named in the same sentence as 19 diseases in open-access papers, as found by Europe PMC text mining. Sharing a sentence is not in itself a finding about the gene and the disease. The quoted sentences say what the papers report.
lung carcinoma (6 papers, 2015 to 2026). "Given the importance of EGFR activity in lung cancer, we confirmed the causal nature of PTPRH loss on EGFR activity through CRISPR mediated knockout of PPTPRH in a NSCLC line by observing increased pEGFR and pAKT." (PMID 36054194, 2022). "Searching for similar mutations in human lung cancer revealed that 5% of all lung cancers had PTPRH mutations." (PMID 36054194, 2022). "Although some studies have demonstrated the involvement of PTPRH in cancer, especially in intestinal tumorigenesis, its role in lung cancer and the molecular mechanisms underlying its regulation have not been clarified." (PMID 26134684, 2015). "The broad implications of this work are that there are a large number of lung cancer patients with PTPRH mutations that could potentially benefit from a revised treatment based on sequencing." (PMID 36054194, 2022). "With this causality and given that 5% of NSCLC tumors have mutations in PTPRH, and an estimated 235,000 cases of lung cancer occurring yearly within the United States, over 10,000 patients who present with PTPRH mutations could potentially benefit from EGFR targeted TKI therapy." (PMID 36054194, 2022). "To further explore the molecular functions of PTPRH in NSCLC, we examined the protein expression levels of PTPRH in lung cancer cell lines and found that PTPRH expression was significantly higher in tumor cells than in normal lung bronchial epithelial cells." (PMID 37974250, 2023). "The ability to use EGFR inhibitors in PTPRH mutant lung cancers is a new area for investigation and is the primary impact of this research." (PMID 36054194, 2022). "5-Aza-2′-deoxycytidine treatment of lung cancer cell lines with low PTPRH expression, restored mRNA PTPRH expression levels." (PMID 26134684, 2015). "5-aza-dC treatment of human lung cancer cell lines with low PTPRH expression restored PTPRH mRNA expression levels indicating that PTPRH is reactivated by DNA hypomethylation during lung tumorigenesis." (PMID 26134684, 2015). "Given the role of EGFR in lung cancer, we explored TCGA data which revealed that a subset of PTPRH mutant tumors shared gene expression profiles with EGFR mutant tumors, but that EGFR mutations and PTPRH mutations were mutually exclusive." (PMID 36054194, 2022). "Patient data revealed that a subset of PTPRH mutant lung cancer did have elevated EGFR activity." (PMID 36054194, 2022). "We attempted a transient knockdown of PTPRH using siRNA in lung cancer cell lines." (PMID 26134684, 2015). "Thus, the role of PTPRH is largely unknown and needs to be clarified in diseases including lung cancer." (PMID 26134684, 2015). "Of 30 top ranked genes, FAM107A, MAMDC2, SOX17, TCF21, PTPRH, and CDO1 have been previously reported with aberrant DNA methylation in lung cancer." (PMID 27610367, 2016). "In three lung cancer cell lines A549, VMRC-LCD, and EBC-1 with low PTPRH mRNA expression, 5-aza-dC treatment induced a marked reduction of DNA methylation and restored PTPRH mRNA expression levels." (PMID 26134684, 2015). "While PTPRH expression was found to be increased in human colon and pancreatic cancer and reduced in advanced human hepatocellular carcinoma, to our knowledge no previous study has examined its expression in lung cancer." (PMID 26134684, 2015).
non-small cell lung carcinoma (6 papers, 2015 to 2026). A group of at least three distinct histological types of lung cancer, including non-small cell squamous cell carcinoma, adenocarcinoma, and large cell carcinoma. "Both datasets contained PTPRH mutations within several cancers, including a mutation prevalence of approximately 5% in non-small cell lung cancer (NSCLC)." (PMID 36054194, 2022). "In addition, another report showed that PTPRH is regulated by epigenetic DNA hypomethylation and is associated with prognosis in patients with non-small-cell lung cancer." (PMID 34367321, 2021). "PTPRH has been shown to be overexpressed in different adenocarcinomas, including colon, pancreas and non-small cell lung cancer." (PMID 32231398, 2020). "The aim of the present study was to clarify the significance of PTPRH expression and its regulation by DNA methylation in non-small cell lung cancer (NSCLC), especially in lung adenocarcinoma (LADC)." (PMID 26134684, 2015).
hepatocellular carcinoma (3 papers, 2015 to 2022). A malignant tumor that arises from hepatocytes. "Within cancers of the liver, lower PTPRH expression is associated with poorly differentiated hepatocellular carcinomas (HCC) relative to higher levels in normal liver tissue." (PMID 36054194, 2022). "Clinically, the protein abundance of PTPRH is inversely related to the aggressiveness of human hepatocellular carcinoma patients, and enforced expression of PTPRH inhibits the migration and growth of human hepatocellular carcinoma cells." (PMID 34187934, 2021). "In contrast, PTPRH was found to be downregulated in advanced human hepatocellular carcinoma and inhibited the proliferation of cultured cells." (PMID 26134684, 2015). "Furthermore, overexpression of PTPRH in HCC cell lines with low PTPRH expression drastically reduced cellular motility and growth rate in vitro, suggesting PTPRH has a tumor suppressive role within hepatocellular carcinoma." (PMID 36054194, 2022).
neuroblastoma (3 papers, 2017 to 2022). Neuroblastoma (NB) is the most common solid, extracranial childhood tumor. "Collectively, these observations suggest that PTPRH functions as a tumor suppressor in high-risk neuroblastomas." (PMID 35246212, 2022). "PTPRH protein is highly expressed in neuroblastomas, in association with tumor low stage and patient low risk, and PTPRH mRNA is induced in neuroblastoma cells upon retinoic acid differentiation." (PMID 34957126, 2021). "In our study, we found that (a) PTPRH exhibits recurrent ASE in neuroblastoma, (b) low expression of PTPRH is associated with adverse patient outcomes, and (c) knockdown of PTPRH increases proliferation and wound healing in neuroblastoma cell lines." (PMID 35246212, 2022). "Since the related PTPRO enzyme, which is mainly expressed in the developing nervous system, dephosphorylates Trk receptors, a role is possible for PTPRH in the direct regulation of Trk signaling in neuroblastoma cells." (PMID 34957126, 2021). "PTPRH is located on chromosome 19q, which rarely undergoes SCNA in neuroblastoma, and ASE of PTPRH is not correlated with SCNA score." (PMID 35246212, 2022). "In neuroblastoma, 5 out of 68 testable samples exhibit ASE, compared to 1 out 139 testable adrenal gland tissues from GTEx (Fisher’s exact test p-value = 0.015); PTPRH is not expressed in the whole blood." (PMID 35246212, 2022).
stomach cancer (3 papers, 2015 to 2021). "PTPRH is known as stomach cancer-associated protein tyrosine phosphatase 1 (SAP-1), and it is also a receptor-type protein tyrosine phosphatase that locates specifically at microvilli of the brush border in gastrointestinal epithelial cells." (PMID 34367321, 2021). "PTPRH, also known as stomach cancer-associated PTP-1 (SAP-1), was first identified as a transmembrane-type PTP abundant in a subset of pancreatic and colorectal cancer cell lines." (PMID 26134684, 2015). "Protein tyrosine phosphatase receptor type H (PTPRH), also named stomach cancer-associated protein tyrosine phosphatase-1 (SAP-1), was first identified as a receptor PTP in the human stomach cancer cell line KATO-III." (PMID 29558404, 2018).
breast carcinoma (2 papers, 2019 to 2021). "Whole genome sequencing of tumors derived from a mouse model of breast cancer, MMTV-PyMT, identified a highly conserved mutation in PTPRH, which increases the phosphorylation of EGFR." (PMID 34187934, 2021). "The high expression of PTPRH mRNA was significantly correlated with high EGFR mRNA expression in 13 HER2-positive breast cancer cell lines, suggesting the functional significance of PTPRH in the dephosphorylation of EGFR in HER2-positive breast cancer cells." (PMID 34187934, 2021). "Interestingly, up-regulation of PTPRH has also been detected in breast cancer cell lines grown upon differentiation conditions." (PMID 31837707, 2019). "Taken together, it is likely that the regulation of EGFR phosphorylation through PTPRH activation and RhoB degradation by the CUL3/KCTD10 E3 complex is conserved in HER2/EGFR-double positive breast cancer cells." (PMID 34187934, 2021). "Our present results suggest that CNKSR1 serves as an oncoprotein by inactivating PTPRH, a tumor-suppressive EGFR phosphatase, in HER2-positive breast cancer cells." (PMID 34187934, 2021). "From a drug-discovery standpoint because inhibition of the PTPRH/CNKSR1 complex releases PPTRH leading to its activation, inhibitors of this PTPRH/CNKSR1 interaction could represent novel drugs for HER2-positive breast cancers." (PMID 34187934, 2021).
colorectal cancer (2 papers, 2015 to 2023). A primary or metastatic malignant neoplasm that affects the colon or rectum. "The protein tyrosine phosphatase H receptor (PTPRH) is known to regulate the occurrence and development of pancreatic and colorectal cancer." (PMID 37974250, 2023). "Recent studies have shown that PTPRH regulates the occurrence and development of colorectal cancer and NSCLC." (PMID 37974250, 2023).
lung adenocarcinoma (2 papers, 2015 to 2021). A carcinoma that arises from the lung and is characterized by the presence of malignant glandular epithelial cells. "The aim of the study is to explore the prognosis value of PTPRH in patients with lung adenocarcinoma (LUAD)." (PMID 34367321, 2021).
pancreatic cancer (2 papers, 2015 to 2021). "In addition, the protein and mRNA expression of PTPRH in clinical tissues was detected by using immunohistochemistry and qRT-PCR, respectively, and PTPRH was found to be highly expressed in LUAD, which was consistent with the results in epithelial ovarian cancer and pancreatic cancer cell." (PMID 34367321, 2021).
Airway obstruction (1 paper, 2023). Obstruction of conducting airways of the lung. "Previous studies have shown that PTPRH can reduce protein phosphorylation through related signaling pathways to alleviate airway obstruction in patients with asthma." (PMID 37974250, 2023).
Lynch syndrome (1 paper, 2014). An autosomal dominant hereditary neoplastic syndrome characterized by the development of colorectal carcinoma and a high risk of developing endometrial carcinoma, gastric carcinoma, ovarian carcinoma, renal pelvis carcinoma, and small intestinal carcinoma. "Whole-genome DASL-based gene expression profiling based on 18.6 k genes identified 349 significantly deregulated genes with up-regulation of e.g. PTPRH, BIRC3, SHH and TNFRSF6B in Lynch syndrome tumors." (PMID 24848881, 2014).
skin cancer (1 paper, 2022). "There is therefore a compelling reason to explore the role of PTPRH mutations in the future in skin cancer to determine if these mutations act in the same manner." (PMID 36054194, 2022).
tumor (14 papers, 2015 to 2026). "Increased PTPRH levels have been linked to larger tumor size, advanced clinical stage, and poor prognosis in NSCLC." (PMID 40740483, 2025). "A strong association has been demonstrated between elevated PTPRH expression and enhanced tumor aggressiveness." (PMID 40740483, 2025). "Testing two tumor lines from patients with naturally occurring PTPRH mutations revealed a sensitivity to EGFR inhibitors." (PMID 36054194, 2022). "A pan-cancer analysis of human PTPRH mutations found numerous cancers harboring mutations, suggesting mutated PTPRH may play a role in tumor development across the spectrum of cancer types." (PMID 36054194, 2022). "Functionally, PTPRH promoted tumor cell proliferation, migration, invasion, and xenograft tumor growth, while simultaneously inhibiting apoptosis and enhancing angiogenesis via the VEGF pathway." (PMID 42113318, 2026). "Given the increased research focus on tumor metabolic abnormalities, the impact of PTPRH on the biological behavior and glycolysis of tumor cells has potential clinical applications." (PMID 37974250, 2023). "We retrospectively collected clinical data from 80 patients with NSCLC, grouped according to age, sex, tumor diameter, and clinical tumor stage, to compare the relationship between PTPRH expression levels and clinical characteristics." (PMID 37974250, 2023). "The results showed that PTPRH was highly expressed in clinical patient tissue samples and closely related to tumor diameter and clinical stage." (PMID 37974250, 2023). "Confirmation that PTPRH acts as a tumor suppressor will require in vivo experiments that are beyond the scope of this study." (PMID 35246212, 2022). "The expression patterns of PTPN1 in human NB cells and NB tumor samples was investigated, in comparison with other PTPs, including PTPRH, PTPRZ1, and PTEN." (PMID 31837707, 2019). "In addition, we identify some genes that have recurrent ASE outside of common SCNA regions, including TFAP2B and PTPRH, both of which have low expression in stage 4 disease and evidence for tumor suppressor activity." (PMID 35246212, 2022). "In summary, we report that PTPRH promotes glycolysis, proliferation, migration, and invasion via the PI3K/AKT/mTOR signaling pathway in NSCLC and ultimately promotes tumor progression, which can be regulated by LY294002 and 740Y-P." (PMID 37974250, 2023). "We first performed immunohistochemistry experiments on tumor tissues from mice, and the results showed that p-AKT and p-PI3K were relatively downregulated in the sh-PTPRH group compared to the sh-NC group." (PMID 37974250, 2023). "At least two of these genes have evidence for tumor suppressor activity including the transcription factor TFAP2B and the protein tyrosine phosphatase PTPRH." (PMID 35246212, 2022). "NB tumor samples from 44 patients were analysed by immunohistochemistry using specific antibodies against PTPN1, PTPRH, PTPRZ1, and PTEN." (PMID 31837707, 2019). "PTPRH and PTPRZ1 were expressed in a large number of NB tumor samples, mostly displaying a cytoplasmic granular staining pattern." (PMID 31837707, 2019). "This stemness-associated signature integrates developmental drivers such as PTPRH, AHNAK2, PCDH7, metabolic regulators CPS1, SFTPB, and hypoxia-responsive factors such as TCN1, TMPRSS11E, reflecting the multifaceted nature of OSA-induced tumor evolution." (PMID 41584048, 2026). "In conclusion, PTPRH affects glycolysis in NSCLC cells via the PI3K/AKT/mTOR signaling pathway and ultimately promotes tumor progression in NSCLC, which could be regulated by LY294002 and 740Y-P." (PMID 37974250, 2023). "PTPRH expression was closely correlated with the tumor diameter and clinical stage of NSCLC patients but not with the age and sex of patients with NSCLC." (PMID 37974250, 2023). "Moreover, SEMA3A, PTPRH and IFIT2 were found to have significant effects on tumour inhibition and functioned as promising therapeutic agents for cancers." (PMID 33145887, 2021).
tumor (continued). "The PTPRH mRNA expression levels were significantly higher in tumorous tissues compared with the corresponding non-cancerous tissues." (PMID 26134684, 2015). "Also, we identified novel predicted tumor-suppressive ligands (SLIT3, DCN, CCN3, THBS1, INHA and INHBA), proteins (DNASE1L3, SULF1, PTEN, OAS1, and DAB2IP), and receptors (P2RX4, CDHR2, PTPRJ, and PTPRH) in MSC1 cells." (PMID 40564222, 2025). "Molecular factors such as PTPRH, CPNE1, APLN, PLOD1, SPAG4, B7‐H3, and SIK2 have been shown to facilitate carcinogenesis and glycolysis via PI3K/AKT induction, whereas inhibitors of this pathway reduce glycolytic flux, diminish tumor growth, and increase sensitivity to anticancer drugs." (PMID 40740483, 2025).
cancer (10 papers, 2015 to 2024). A tumor composed of atypical neoplastic, often pleomorphic cells that invade other tissues. "PTPRH (also known as stomach cancer-associated protein-tyrosine phosphatase; SAP-1) is a transmembrane-type phosphatase that possesses a catalytic domain in its cytosolic region and fibronectin type III-like repeats in its extracellular region containing multiple N-glycosylation sites." (PMID 34187934, 2021). "In recent years, studies have shown that PTPRH regulates the occurrence and development of cancer, but the correlation of PTPRH expression with glycolysis is still unclear." (PMID 37974250, 2023). "Correlation analysis showed that PTPRH expression in cancer tissues was correlated with SUVmax, MTV, and TLG." (PMID 37974250, 2023). "PTPRH may inactivate Akt and promote apoptosis in cancer cells." (PMID 35246212, 2022).
PTPRH also shares sentences with these, for which no sentence is quoted: adenocarcinoma (1 paper); asthma (1); diabetes (1); lymph node metastasis (1); retinal degeneration (1).